LIAT1 (ligand of ATE1)
Description:
Participates in nucleolar liquid-liquid phase separation (LLPS) through its N-terminal intrinsically disordered region (IDR). May be involved in ATE1-mediated N-terminal arginylation.
Synonyms: C17orf97; LOC400566; CK20
Tractability: PROTAC: ubiquitination databases record sites on it.
Gene: Protein-coding gene on chromosome 17 (410,325 to 431,062, forward strand). Ensembl gene ENSG00000187624.
Subcellular location: Nucleus, nucleolus; Cytoplasm
Subcellular location (Human Protein Atlas): Nucleoli; Cytosol
Gene Ontology:
Molecular function: molecular condensate scaffold activity
Biological process: membraneless organelle assembly; protein arginylation
Cellular component: cytoplasm; nucleolus
Genetic constraint (gnomAD): Loss-of-function variants: 12 observed, 5.25 expected, observed/expected ratio (o/e) 2.29. That is too few expected variants to judge how well the gene tolerates losing a copy. Missense variants: 490 observed, 539.6 expected, observed/expected ratio (o/e) 0.91, 90% interval 0.84 to 0.98. Synonymous variants: 238 observed, 228.13 expected, observed/expected ratio (o/e) 1.04, 90% interval 0.94 to 1.16.
Homologues: Orthologues: chimpanzee LIAT1 (93% identical), dog LIAT1 (38% identical), mouse Liat1 (33% identical), rat Liat1 (32% identical).
Diseases named in the same sentence as LIAT1 in open-access papers:
LIAT1 is named in the same sentence as 6 diseases in open-access papers, as found by Europe PMC text mining. Sharing a sentence is not in itself a finding about the gene and the disease.
LIAT1 shares sentences with these, for which no sentence is quoted: Alzheimer disease (1 paper); bladder cancer (1); neurodevelopmental disorder (1); Parkinson disease (1); schizophrenia (1); tumor (1).